EGFR (epidermal growth factor receptor)
Diseases named in the same sentence as EGFR in open-access papers (continued):
Sharing a sentence is not in itself a finding about the gene and the disease.
lung cancer (continued). "The ectopic distribution of the EGFR is an unfavorable marker in various cancers including lung cancer, breast cancer, cervical cancer, and head and neck squamous cell carcinoma, which is related to radiotherapy resistance and dysregulation of the intracellular reduction/oxidation (ReDox) state." (PMID 34298665, 2021). "Molecular dynamics (MD) simulations, as a widely used method in researching about lung cancer, were implemented on EGFR-RTK heterodimer structures, and three- dimensional Alpha Shape modeling was subsequently applied to each MD trajectory frame for extraction of geometrical properties." (PMID 34112110, 2021). "Moreover, the targeted therapies have significantly improved clinical outcomes in a subset of lung cancer patients whose tumors harbor EGFR, ALK, and HER2 alterations." (PMID 33505535, 2021). "The aim of our study was to determine whether the protein cell division cycle-associated protein 3 (CDCA3) might be a biomarker for TKI response in EGFR mutant lung cancer." (PMID 34572879, 2021). "Similarly, restoration of E-cadherin expression significantly increases the sensitivity to epidermal growth factor receptor inhibitor gefitinib in lung cancer cells." (PMID 34552882, 2021). "When gefitinib blocks EGFR, lung cancer may further stimulate tumor growth through compensatory receptors." (PMID 34059647, 2021). "In recent decades, based on the rapid development of high throughput technology, numerous biomarkers have been identified and applied to targeted treatment, such as HER2 (human epidermal growth factor receptor 2) in breast cancer and EGFR (epidermal growth factor receptor) in lung cancer." (PMID 33902514, 2021). "Thus, our findings aid correct interpretation of the published literature by extending and updating older results in the context of contemporary treatment for EGFR+ lung cancer." (PMID 33898315, 2021). "Our findings propose that strategies to upregulate CDCA3 levels might improve TKI response in EGFR mutant lung cancer." (PMID 34572879, 2021). "Furthermore, we found that NEDD4 promotes lung cancer cell migration by facilitating the EGFR-dependent lysosomal secretion of cathepsin B." (PMID 34833029, 2021). "Notably, the GE11 peptide binds specifically to EGFR, which is overexpressed in various cancers including breast cancer, lung cancer, and glioma." (PMID 34575511, 2021). "Flow cytometric apoptotic analysis revealed that the co-treatment of curcumin (10 ng/mL) and gefitinib (0.1 mol/L) significantly augmented the apoptosis in NCI-H1975 lung cancer cells by blocking EGFR signalling pathways, notably Akt and ERK1/2 phosphorylation." (PMID 34299604, 2021). "Current studies on the efficacy of EGFR inhibitors in lung cancer." (PMID 34722241, 2021). "EGFR has emerged as an important therapeutic target, particularly in the context of lung cancer." (PMID 34610265, 2021). "Moreover, up-regulation of AURKA/PLK/CDK1 contributes to PI3K inhibitor resistance in glioblastoma, and AURKA drives the evolution of resistance to EGFR inhibitor in lung cancer." (PMID 34359608, 2021). "Mechanistically, integrin β3 is induced by increased levels of TGFβ1 in acquired TKI-resistant lung cancer, which indicates the TGFβ1/integrin β3 axis as a potential target for combination therapy in EGFR-mutant lung cancer to overcome acquired resistance to EGFR TKIs." (PMID 34976811, 2021). "In lung cancer, for example, YAP1 activation confers resistance to therapies targeted against common lung cancer oncogenes, such as anaplastic lymphoma kinase (ALK), BRAF or mutated epidermal growth factor receptor (EGFR) tyrosine kinase." (PMID 34685695, 2021). "In China, Chinese medicines and their active ingredients have been widely used to treat lung cancer including TKI-resistant NSCLC18,41-45, and some of them have shown a synergistic inhibitory effect and lower TKIs resistance in EGFR L858R+T790M-Mutated H1975 Cells 18,32-35." (PMID 33758606, 2021).
lung cancer (continued). "After lung cancer subtyping is complete, non LUSC are evaluated for targetable driver genomic alterations such as epidermal growth factor receptor (EGFR) mutations, anaplastic lymphoma kinase (ALK) rearrangements, c-Ros oncogene 1 (ROS1) rearrangements, and BRAF V600E mutation." (PMID 33937015, 2021). "Interestingly, the number of HLA class I-presented peptides identified in melanoma and EGFR-mutant lung cancer was roughly similar." (PMID 34391887, 2021). "In general, previous studies based on patients with lung cancer from Xuanwei/Qujing showed that a higher proportion of EGFR compound mutations and KRAS mutations were observed, although EGFR mutation rate in patients with lung cancer patients from Xuanwei was still controversial." (PMID 33928034, 2021). "In addition, upregulation of the TPX2-S121 and S125 sites likely correlated with the reported role of AURKA kinase and its coactivator TPX2 in response to chronic EGFR inhibition to mitigate drug-induced apoptosis in resistant lung cancer cells." (PMID 33953186, 2021). "Therefore, the present study focused on EGFR as it is widely expressed in several types of tumor, such as gastric, liver, colorectal and lung cancer." (PMID 34025789, 2021). "Similar to a previous study, our study further confirmed that ANXA1 is overexpressed in lung cancer cells with or without EGFR mutations." (PMID 34439260, 2021). "To chemically probe the function of AXL in the context of collateral gefitinib resistance, we used YD, an antitumor agent we previously characterized to have concurrent AXL-dependent inhibitory mode-of-action in addition to having EGFR-targeting activity in gefitinib-resistant lung cancer models." (PMID 33850249, 2021). "Recently, epidermal growth factor receptor-tyrosine kinase inhibitors (EGFR-TKIs) gefitinib, erlotinib, and AZD-92912 have been used to treat unresectable or recurrent lung cancer and have shown significantly improved clinical outcomes in patients with NSCLC with EGFR mutations." (PMID 33787673, 2021). "Whether these mutations can be combined with NOTCH1, EGFR and ARID1A mutations as tumor markers in the diagnosis of early lung cancer merits further investigation." (PMID 34136379, 2021). "By analyzing the expression profiles of EGFR and PLK1 in lung cancer patients using TCGA data from cBioPortal, we found that the expression levels of PLK1 and EGFR were correlated positively in lung cancer patients (Spearman factor 0.32, p = 1.65 × 10−9; Pearson factor 0.24, p = 1.159 × 10−5)." (PMID 34503223, 2021). "EGFR-mutant NSCLC is the most prevalent molecular subtype in Asian lung cancer patients." (PMID 34113560, 2021). "Finally, the lung cancer specimens from patients with acquired resistance to EGFR‐TKI showed increased expression of ZEB1, BMI1, and ALDH1A, than in specimens before treatment." (PMID 33764690, 2021). "Moreover, its ability to inhibit EGFR phosphorylation in lung cancer cells overexpressing wild-type EGFR (A549 cell lines) is well established." (PMID 34769263, 2021). "Moreover, knockdown of CMTM7 delays EGFR internalization and degradation by reducing Rab5 activation in lung cancer cells." (PMID 34281589, 2021). "Furthermore, we demonstrated that EGFR‐targeting peptides and nanobodies facilitated specific uptake of RBCEVs by EGFR‐positive lung cancer cells in vivo." (PMID 33643546, 2021). "In addition, induction of HIF-1 by EGFR can make A549 lung cancer cells resistant to another type of PCD called anoikis under the lipid raft-disrupting stress." (PMID 34926310, 2021). "In addition, we identified that inhibition of SOX2‐OT and reduced expression of SOX2/GLI‐1 sensitizes lung cancer cells to EGFR/TKI‐erlotinib or cisplatin‐based treatment." (PMID 33433063, 2021).
lung cancer (continued). "In addition, increasing the levels of CDCA3 enhances TKI sensitivity in models of TKI-resistant EGFR mutant lung cancer." (PMID 34572879, 2021). "Second, the main targets of clinical lung cancer targeted drugs are EGFR, ALK, etc.." (PMID 34681590, 2021). "However, some studies have also demonstrated that heterogeneous EGFR-mutant lung cancer patients can still exhibit good responses to EGFR-TKIs." (PMID 33671000, 2021). "Nevertheless, 10%–20% of lung cancer patients with wild‐type EGFR gained a therapeutic advantage from EGFR TKIs treatment, which implied that there are underlying molecular mechanisms that determine the efficacy of EGFR TKIs and are independent of EGFR somatic mutations." (PMID 33314735, 2021). "Our results indicated that PFKL/MET inhibitors in combination with EGFR TKIs could be synergistic in the clinical management of lung cancer." (PMID 34368128, 2021). "The level of lncRNA and EGFR in lung cancer and normal lung tissue was analyzed using TCGA data." (PMID 33422052, 2021). "Some studies have also demonstrated that EVs from EGFR-mutant lung cancer cells may affect sensitivity to EGFR-TKIs or chemotherapy." (PMID 33671000, 2021). "Supporting its important oncogenic role independent of upstream EGFR signaling, MOS has been described in lung cancer models as essential activator of both MEK-ERK and phosphoinositide 3-kinase (PI3K)-AKT pathways in an EGFR-independent manner, compensating for the loss of EGFR activity." (PMID 34070180, 2021). "A classic example of the third mechanism of acquired resistance—lineage transformation—is the histologic transformation of lung adenocarcinoma subtype to small cell carcinoma subtype, which accounts for 5–15% of EGFR-mutant lung cancer patients with acquired resistance to EGFR TKIs." (PMID 34071428, 2021). "In addition to EGFR mutations, ctDNA testing was also used for monitoring response or resistance to ALK inhibitors therapy in patients with lung cancer via identification of appearance of ALK variations, including ALK point mutations and rearrangements." (PMID 34422670, 2021). "Immunotherapy has been less successful in EGFR-mutant lung cancer, in part, because of its low TMB." (PMID 34391887, 2021). "Patients with KRAS mutations showed the lowest incidence for VTE among the analyzed driver genes, and both KRAS and EGFR mutations were proved no significant relation with VTE risks in patients with lung cancer." (PMID 33996610, 2021). "Based on the importance of EGFR signaling in lung cancer, the known cooperation between EGFR and SRC proteins, and evidence of elevated SRC activity in human NSCLC, several studies have also evaluated the therapeutic effectiveness of SRC kinase inhibitors in lung cancer." (PMID 34944848, 2021). "Previous studies showed that selenium treatment could downregulate EGFR mRNA levels in human biopsy-derived glima cells and lung cancer cell lines." (PMID 34393797, 2021). "Over-expression of EGFR appear in nearly 60% of NSCLC patients, who frequently harbor EGFR mutations (like L858R) that will lead to aberrant singling, enhanced cell proliferation and progression of lung cancer." (PMID 34112110, 2021). "In addition, the discovery of EGFR signaling pathway inhibition through lncRNA can shed light on the mechanism as a new potential target for lung cancer treatment." (PMID 33422052, 2021). "Thus, targeting EGFR activity with cytotoxic chemotherapy is a potential therapeutic method for EGFR wild-type lung cancer." (PMID 34445110, 2021).
lung cancer (continued). "Treatment options for lung cancers include surgery, chemotherapy, radiotherapy as well as monoclonal antibodies targeting epidermal growth factor receptor (EGFR), anaplastic lymphoma kinase (ALK), programmed cell death 1 (PD-1) and programmed cell death ligand 1 (PD-L1)." (PMID 34765548, 2021). "Non‐small cell lung cancer (NSCLC) is a major type (~85%) of lung cancer, and its targeted therapy is tried such as epidermal growth factor receptor tyrosine kinase inhibitors (EGFR‐TKIs); however, the treatment still limited due to acquired resistance and deficient efficacy." (PMID 33982869, 2021). "Acquired resistance occurred in the majority of nonsmall cell lung cancer (NSCLC) patients receiving epidermal growth factor receptor-tyrosine kinase inhibitors (EGFR-TKIs) therapy, and this may be related to the activation of the HIF-1 pathway." (PMID 33763171, 2021). "Moreover, we determined the expression of PGK1 with several typical genetic alteration events in lung cancer, including EGFR mutants, KRAS mutants, and ALK fusions in The Cancer Genome Atlas (TCGA) clinical cohort." (PMID 34091600, 2021). "Moreover, the activation of EGFR with the treatment of EGF in lung cancer cells was positively correlated with TOPK phosphorylation." (PMID 34066486, 2021). "Moreover, it has been reported that AURKA drives the evolution of resistance to EGFR inhibitors in lung cancer, and the aberrant activation of AURKA contributes to the highly aggressive nature of lymphoproliferative disorders." (PMID 34359608, 2021). "Lung cancer is a complex disease associated with gene mutations, particularly mutations of Kirsten Rat Sarcoma Viral Oncogene Homolog (KRAS) and epidermal growth factor receptor (EGFR)." (PMID 34830377, 2021). "However, SCAMP3 was also reported to function as a novel tumor suppressor in lung cancer by modulating EGFR signaling and cytokinesis." (PMID 34426610, 2021). "In our study, we found that RESV, when used alone, promoted the accumulation of cells in the G0/G1 phase and S or G2/M phase depending on the lung cancer cell lines, with the most significant arrest in G2/M phase for HCC827 cell line, which is the representative of EGFR-mutant lung cancer." (PMID 33652978, 2021). "EGFR 20IN alterations in the young lung cancer group were much enriched." (PMID 35096611, 2021). "With the approval of the use of EGFR-TKIs in EGFR mutation-positive lung cancer patients, EGFR mutation testing is generally recommended to non-squamous NSCLC patients." (PMID 33961689, 2021). "This could be attributed at least in part by a mediation of EGFR signaling in lung cancer cells and/or the inhibition of cellular metabolism by the drug." (PMID 34371754, 2021). "However, only few studies have explored the different outcomes in patients with EGFR-mutant lung cancer who received different radiotherapy modes, especially after considering the Lung-molGPA." (PMID 34847914, 2021). "A possible application of this gene signature is to discriminate lung cancer patients who may benefit from specific treatments (i.e., EGFR tyrosine kinase inhibitors)." (PMID 35295134, 2021). "However, it was possible to detect overexpressed GLI1‐AS in both EGFR‐wild‐type lung cancer cells A549 and NCI‐H2347." (PMID 33433063, 2021). "To check whether an IR-induced G2 checkpoint defect is specific for TrkA/NTRK1 or is a general consequence of tyrosine kinase activation in cancer cells, we used EGFR-overexpressing lung cancer cells, A549 and H1975, as a control." (PMID 34885133, 2021). "Gefitinib is the first EGFR TKI approved for clinical use in lung cancer patients." (PMID 33314735, 2021). "Anti-ER and EGFR molecules are used for dual-mode-strengthened lung cancer therapy." (PMID 35008242, 2021). "We applied the PLS-DA to distinguish the volatile metabolites between lung cancer patients with and without EGFR mutation." (PMID 34193905, 2021).
lung cancer (continued). "Moreover, ERK-1/2 signaling chemo-sensitizes drug-resistant lung cancer cells to WZ4002 (EGFR inhibitor)." (PMID 33996789, 2021). "EGFR, as a common biomarker in lung cancer, was widely tested to guide clinical treatment." (PMID 33777727, 2021). "A number of TKIs are approved for use in EGFR-mutant lung cancer." (PMID 34680249, 2021). "Tumor extracellular matrix (ECM) composition can play a role in EGFR-dependent lung cancers." (PMID 34976811, 2021). "Furthermore, the expression of EGFR mRNA was significantly reduced by miR-125a-5p (down-regulated in lung cancer) and consequently inhibited cell proliferation and efficiently triggered apoptosis." (PMID 34830377, 2021). "It is worth considering how these findings might be translated clinically to improve the therapeutic response to TKIs in EGFR mutant lung cancer." (PMID 34001994, 2021). "During the past 20 years, important progress has been made in our understanding of the molecular pathogenesis of lung cancer, whose malignant transformation has been demonstrated to result from the accumulation of genetic aberrations such as in EGFR, KRAS, and ALK." (PMID 33288886, 2021). "In this study, we further investigated how Nrf2 regulates motility in NSCLC cells based on our previous findings, which showed that high activation of Nrf2 due to Keap1 mutation promotes migration ability both in vitro and in vivo in EGFR-TKI resistant lung cancer cells." (PMID 33441941, 2021). "Epidermal growth factor receptor (EGFR) is closely related to lung cancer." (PMID 34193120, 2021). "In addition, we confirmed that YAP regulates the transcription of p62 via ERK, and YAP inhibition can significantly decrease the expression of p62 in EGFR‐TKI‐resistant lung cancer." (PMID 33486901, 2021). "Curcumin also showed dose-dependent inhibition of MyD88, TLR4, and EGFR in lung cancer cell lines." (PMID 34867402, 2021). "Finally, we suggest that targeting YAP‐p62 signaling axis can be useful to suppress the EGFR‐TKI‐resistant lung cancer." (PMID 33486901, 2021). "LncRNAs regulate the sensitivity of lung cancer cells to EGFR‐TKIs chiefly through one of the following mechanisms: 1) MAPK/ERK signaling pathway, 2) PI3K/AKT/mTOR signaling pathway, 3) STAT3 signaling pathway, 4) mitochondrial pathway, 5) cell cycle progression, or 6) EMT." (PMID 33931980, 2021). "Furthermore, the survival rates until first progression (FP) showed that the expression levels of PLK1 and EGFR mRNA and survival rates were correlated inversely in human lung cancer (n = 596, HR = 1.98, log rank P = 8.3 × 10−7)." (PMID 34503223, 2021). "Importantly, IκBα silencing by interference RNA expression was found to rescue EGFR-mutant lung cancer cells from erlotinib (EGFR-tyrosine kinase inhibitor) treatment." (PMID 34572464, 2021). "In the study, lung cancer cells were pulsed with osimertinib, a third-generation EGFR TKI." (PMID 34952897, 2021). "Interestingly, Huang and collaborators demonstrated that, in lung cancer, EGFR-enriched exosomes induce tDCs; tDCs, in turn, induce tumor specific Tregs, which inhibit the specific anti-tumor CTL response." (PMID 34571894, 2021). "Unlike patients with lung cancer harboring EGFR mutations or ALK translocations, diseases for which targeted agents typically achieve 60 to 80% response rates, KRAS G12C inhibitors such as sotorasib and adagrasib typically yield 40 to 50% response rates." (PMID 34680229, 2021). "To date, genetic studies have demonstrated that EGFR polymorphisms may modify the risk for head and neck squamous cell carcinoma (HNSCC), lung cancer, renal cancer, and so on." (PMID 34501555, 2021). "No somatic variants—such as activating mutations of EGFR—that confer sensitivity to molecularly targeted drugs in non–small cell lung cancer were identified." (PMID 34140559, 2021). "Our study is the first to study the lung cancer patients’ mutation spectrum in the Chinese population without EGFR or ALK driver gene mutations." (PMID 33643802, 2021).